IL33 (interleukin 33)
Diseases named in the same sentence as IL33 in open-access papers (continued):
Sharing a sentence is not in itself a finding about the gene and the disease.
asthma (continued). "Additionally, an anti-IL33 antibody and an anti-IL33 receptor (ST2) antibody, in separate phase II clinical trials, have recently been evaluated for their ability to treat asthma." (PMID 32397226, 2020). "Although the collected data supports an association between IL-25 and asthma, clinical trials using anti-IL-25 antibodies, as for TSLP and IL-33, have not yet been conducted." (PMID 33255348, 2020). "The IL-33 inhibitor (CNTO-7160), which is currently being examined in clinical trials for asthma and atopic dermatitis, may be employed as a new therapy for fibrosis in patients with SSc, since anti-fibrotic effects have been observed on the lung." (PMID 32679721, 2020). "While this group found no role for the IL-33-producing ILC2 cells in influenza exacerbation of asthma, another group using the same HDM-sensitized murine model implicated ILC2s as well as CD4 + T cells." (PMID 33101299, 2020). "Although IL-33-responsive TH cells have been studied in many diseases including asthma, currently there is a lack of studies examining TH cells that respond to IL-33 in the bone marrow." (PMID 32466530, 2020). "Binding of extracellular soluble IL-33 to IL-33 receptors on T helper type-2 (Th2) cells and type-2 innate lymphoid cells (ILC2 cells) is important for driving Th2 responses, such as those observed in parasitic infections, allergy, and asthma." (PMID 33376451, 2020). "In light of the strong indication that they act as upstream drivers of T2-mediated disease, TSLP, IL-33, and IL-25 have attracted a lot of interest as potential therapeutic targets in asthma, and monoclonal antibodies targeting TSLP and IL-33 are currently under clinical evaluation." (PMID 33255348, 2020). "In children with severe asthma, however, increased submucosal expression of IL-33, an epithelial-derived alarmin, and IL-33 positive non-residential cells are found in the airway wall." (PMID 32188435, 2020). "Co-culture with epithelium and moMφs significantly increased TSLP in asthma and did not change IL-33 and IL-17A mRNA expression in moDCs." (PMID 32842623, 2020). "Even though IL-33 has not been investigated as a mediator in a group suffering from these two co-morbid diseases, it can be hypothesized that this alarmin enhances airway remodeling and fibrosis occurring in the course of asthma due to its increased level caused by co-morbid OSA." (PMID 31057533, 2019). "IL-33 was found to be essential in A. alternata induced steroid resistant asthma by promoting TH2 cells and ILC2 that were not inhibited by steroids." (PMID 31824491, 2019). "IL-33 administration to mast cells activated the NF-κB and MAP signaling pathways, leading to the initiation of inflammation and the progression of several diseases, such as asthma, allergy, anaphylaxis, and microbial infections." (PMID 31640262, 2019). "In our results, although IL-33 plays important role in induction of asthma, the mode of challenge was not affected in asthmatic patterns." (PMID 31823765, 2019). "Recent studies clearly show that not only Th2 cytokines but also other T-cell-related cytokines such as IL-17A and IL-22 as well as epithelial cell cytokines such as IL-25, IL-33, and thymic stromal lymphopoietin (TSLP) are involved in the pathogenesis of asthma." (PMID 30965592, 2019). "Taken together, we detected that airway epithelial cells from asthma patients with neutrophilic phenotype had expected increased expression of IL-8 and CXCL1 while asthmatics with eosinophilic phenotype had an enhanced expression of IL-33." (PMID 31798831, 2019). "Summary of ongoing clinical trials targeting IL-33 pathway in COPD and asthma." (PMID 31057533, 2019). "This suggests that the asthma-like symptoms induced by influenza infection do not greatly affect mortality against viral infection in our experimental model, due to minimal IL-33 secretion." (PMID 31509992, 2019).
asthma (continued). "IL-33 is now being considered a proinflammatory cytokine centrally involved in asthma pathogenesis, which also has not been changed after LEDT." (PMID 30775383, 2019). "Protostemonine (PSN), an alkaloid isolated from Radix Stemonae was found to suppress inflammatory conditions, IL-33 production and polarization of macrophage into AAM phenotype in the lung tissues of a dust mites, ragweed and aspergillus-induced murine asthma model." (PMID 30886621, 2019). "The murine models of both asthma and COPD suggest that IL-33 and the ST2 receptor might be prominent new therapeutic targets for these chronic inflammatory respiratory diseases." (PMID 31057533, 2019). "Different from asthma in which the AAM polarization is pro-inflammatory, IL-33 could prime macrophages into AAM in murine TNBS-induced colitis for inhibiting disease activity and the release of inflammatory mediators." (PMID 30886621, 2019). "For the epithelial environment stage of asthma (allergic sensitization stage), air exposure to allergens induces the secretion of proinflammatory cytokines (Group 1) in the airway epithelium, such as TSLP, IL-6, IL-8, TNF-α, IL-25, IL-33, and GM-CSF." (PMID 31284537, 2019). "Interestingly, IL-33-dependent ILC2 expansion, eosinophilia, Th2 cytokines expression and AHR are also important in aspirin-exacerbated respiratory disease, a severe asthma subtype." (PMID 29987222, 2018). "In the current study, the inflammatory cytokines, IL17A, IL33, and IFNγ, were elevated in serum of patients with both allergic and nonallergic asthma, reflecting an active inflammatory state in all our asthmatic patients." (PMID 30306094, 2018). "In addition, the IL-33/ST2 axis appears to play a pivotal role in Th2-driven chronic inflammatory diseases, such as asthma, inflammatory bowel disease, and allergic rhinitis." (PMID 30034292, 2018). "Our results demonstrate that IL-33 is elevated in EBC collected from non-atopic COPD subjects to the same extent as in asthma." (PMID 29859068, 2018). "Thus, as both LPS/TLR4 and IL-33/ST2 signal via MyD88, there is potential for crosstalk between TLR4 and IL-33R (ST2) on mast cells to promote pathogenesis and exacerbation of asthma." (PMID 29540770, 2018). "The IL-33/ST2 pathway is especially accompanied by strong activation of type 2 innate lymphoid cells, which appear to be an important source of IL-5 and IL-13, which are essential for asthma pathogenesis." (PMID 30257479, 2018). "In rag2−/−IL2−/− mice that lack lymphocytes (including ILC2s), administration of epithelium-derived IL-33 via inhalation does not induce asthma-like inflammation." (PMID 29363055, 2018). "The first monoclonal anti-ST2 antibody, CNTO-7160, was recently designed as a new IL-33 inhibitor; this antibody is being evaluated in phase I clinical trials for the treatment of severe asthma and atopic dermatitis, but no data have been published to date." (PMID 30498500, 2018). "We first compared the wild-type and knockout mice in the IL-33-induced asthma model and found no overt difference between them." (PMID 29593738, 2018). "Taken together, an interaction between IL-33, the cell surface, and soluble IL-33 receptors (ST2L and sST2, respectively) regulates the airway granulocyte (i.e. neutrophil and eosinophil) counts that potentially influence asthma phenotypes." (PMID 30176857, 2018). "In contrast, the expression of TSLP, IL-25, and IL-33 in non-severe asthma patients with CRS group was very weak (respectively)." (PMID 28199345, 2017). "Consequently, targeting IL-25, IL-33, and TSLP is an interesting therapeutic approach for severe asthma and is actively being pursued." (PMID 28725641, 2017). "We investigate whether the augmented Th2-cytokines in CRS might be related to sinonasal tract ILC2s corresponding to enhanced IL-25, IL-33 and TSLP release in severe asthmatics, and be involved in asthma control." (PMID 28199345, 2017).
asthma (continued). "Recent studies have found that cytokine alarmins, including thymic stromal lymphopoietin (TSLP), IL-25, and IL-33, produced by epithelial cells and some hematopoietic cells play important roles in the promotion of TH2 cell development and the initiation of asthma pathogenesis." (PMID 27378934, 2016). "We have previously shown that the innate cytokine IL-33 is relatively steroid resistant and that tissue expression is increased in children with severe asthma (regardless of fungal sensitization)." (PMID 25746970, 2015). "This study provides a mechanism involving IL-33 and ILC2s in RSV mediated human asthma." (PMID 26473724, 2015). "That is, keratinocyte-derived IL-25, IL-33 and/or TSLP may be involved in sensitization to allergens, contributing to the development of not only atopic dermatitis but also asthma." (PMID 26230091, 2015). "We examined the expression and functional role of IL-33 in bronchial biopsies of patients with and without asthma, ex vivo ASM, mast cells, cocultured cells and in a mouse model system." (PMID 25683166, 2015). "Mast cell localization to the ASM-bundle is a notable feature of asthma, and therefore, ASM-derived IL-33 might play an important role in IgE-independent mast cell activation in the asthmatic airway." (PMID 25683166, 2015). "Role of IL-33 in mast cell activation and airway smooth muscle wound repair has also been reported which suggests that IL-33 presents important target to modulate mast cell-airway smooth muscle (ASM) crosstalk in asthma." (PMID 26425339, 2015). "Severe RSV infection during infancy is heavily associated with the development of wheeze and/or allergic asthma during childhood and early adult life, and various genetic studies in humans have identified both IL-33 and ST2 as being key regulators in the development of asthma." (PMID 26473724, 2015). "We show that IL-33 expression was increased in the bronchial epithelium and ASM in asthma." (PMID 25683166, 2015). "IL-33 can interact to ST receptors also known as IL-RL1 largely located on the Th2 helper cell and mast cell and have been understood to play a crucial role in the development of allergic disease such as asthma and atopic dermatitis." (PMID 25202911, 2014). "Asthma is a disease with demonstrated heritability in humans, and several genes, including the IKZF3-ZPBP2-GSDMB-ORMDL3 locus, HLA-DQ, IL1RL1, IL33, TSLP, SLC22A5, SMAD3, and RORA have been consistently associated with asthma in genome-wide association studies (GWAS)." (PMID 23984888, 2013). "GWA data were for example not included, and certain important candidate genes for asthma and allergy (e.g. IL33 or HLA-DQ) were not assessed." (PMID 24260339, 2013). "Clinically, the IL-33/ST2 pathway is considered a major novel target for therapeutic interventions across a range of diseases, including Alzheimer's disease, helminth infections, cardiovascular disease, obesity, asthma and other autoimmune disorders." (PMID 23300625, 2012). "Monoclonal antibodies targeting IL-33, such as tozorakimab and itepekimab, are currently in clinical trials for chronic obstructive pulmonary disease (NCT05166889 and NCT05158387), asthma (NCT04570657), and acute respiratory failure (NCT05624450) and might be repurposed for PAH." (PMID 41564150, 2026). "Interestingly, in a mouse model of virus-induced asthma exacerbation, administration of Poly I:C induced IL-33 gene expression, but not IL-25, in wild-type mice." (PMID 41576028, 2026). "In addition to the typical epithelial alarmin IL‐33, the neuropeptide calcitonin gene‐related peptide (CGRP) was also identified in OVA‐induced mouse models as an activator of ILC2, driving Type 2 inflammation in asthma." (PMID 41568067, 2026). "Additionally, interleukin-33 (IL-33) is another key cytokine that plays a role in the polarization of macrophages through the ST2 receptor, further exacerbating the inflammatory response in asthma." (PMID 40076729, 2025).
asthma (continued). "Unlike TSLP, IL-33 plays a key role in driving virus-induced exacerbations in asthma patients." (PMID 41169790, 2025). "Furthermore, airway damage increases epithelial permeability, enhancing allergen exposure and promoting the release of alarmins [Interleukin-25 (IL-25), Interleukin-33 (IL-33), and thymic stromal lymphopoietin (TSLP)] by epithelial cells, which in turn induce Th2-high asthma." (PMID 40678720, 2025). "However, the absence of studies directly comparing sputum IL‐33 levels in patients with COPD vs. asthma prevents a definitive conclusion about this potential mechanism." (PMID 40492692, 2025). "Furthermore, since HMPV and RSV infection in children has been reported to drive type 2 immune responses, we analyzed the response of epithelial alarmins IL-25, IL-33, and TSLP, which play significant roles in the pathophysiology of asthma by promoting inflammation and airway hyperresponsiveness." (PMID 40143308, 2025). "Biologics targeting IFN-γ, TNF-α, and IL-33 are not yet available for asthma and COPD patients." (PMID 39439801, 2024). "Recently approved or therapeutic trials of monoclonal antibodies against TSLP, IL-33 and its receptor ST2, or mast cells validate the roles of these upstream drivers of type 2 inflammation in asthma; however, they also display efficacy in people with severe asthma who lack T2 features." (PMID 40047886, 2024). "Thus, IL‐33‐targeting therapies may reduce exacerbation in patients with ACO (i.e., COPD plus innate asthma), although further investigations are required." (PMID 38652015, 2024). "This work distinguished P2Y13-R as a new gatekeeper of the nuclear alarmins IL-33 and HMGB1 and recognized that targeting this GPCR via genetic deletion or therapy with a small-molecule antagonist defended against the onset and exacerbation of experimental asthma." (PMID 36675299, 2023). "In addition, posterior probability was >20% between the CDTA locus 17p11.2 (TNFRSF13B) and non-suppurative otitis media, and the NP locus 9p24.1 (IL33) and asthma." (PMID 36653354, 2023). "Furthermore, in terms of predictability, we showed that IL-33 was a significant predictor of osteitis severity, but we did not observe the asthma status and endoscopic scores to be significant predictors." (PMID 38137606, 2023). "Therefore, we hypothesized that CpG-ODN administration suppresses the TSLP-DC pathway by downregulating the IL-33/ST2, thereby alleviating the Th2/Th17 type inflammatory response to smoke-related asthma." (PMID 36834541, 2023). "Eosinophilia can identify asthmatic patients who may benefit more significantly from ICS therapy, and monoclonal antibodies targeting IgE or the type 2 cytokines (IL‐4, IL‐5 and IL‐13) or alarmins (IL‐33, TSLP) benefit patients with the ‘Type‐2‐high’ phenotype of asthma." (PMID 37963721, 2023). "As revealed by the characteristic cytokine (IL-13/IL-33)-induced T2 asthma cellular model, the expression trend of only four lncRNAs, EPB41L4A-AS1, PCAT19, SLC9A3-AS1, and SNHG16, was consistent with the results of RNA sequencing with the stimulation of IL-13 and IL-33." (PMID 35480331, 2022). "A multitude of humanized monoclonal antibodies for asthma treatment are currently undergoing clinical development, which include tezepelumab (targeting TSLP) as well as etokimab, itepekimab, astegolimab (AMG 282), torzorakimab, and melrilimab (GSK3772847) for IL-33." (PMID 36311787, 2022). "Interestingly, it has been suggested that the cellular immune response to IL-33 following RV infection differs between people with and without asthma." (PMID 36077310, 2022). "However, while most of the asthma model hallmarks such as AHR did not present significant changes between the NLRP3 deficient mice and the WT, the levels of IL13 and IL33 were slightly but significantly attenuated." (PMID 36189256, 2022).
asthma (continued). "Interestingly, HDM challenge also markedly and significantly elevated the expression of IL-25, IL-33 and TSLP (three cytokines also thought to a play pivotal role in the initiation of asthma) in the lung tissue of both WT and Il9−/−mice compared with saline challenge." (PMID 35524325, 2022). "In a mouse model of asthma, IL-25-induced ILC2s and IL-33-induced ILC2s contributed 50~80% of the total IL5 and IL-13 production in the lung, although stimulation with IL-25 or IL-33 separately did not cause excessive lung reactions." (PMID 34177881, 2021). "However, the most profound changes after UPM stimulation for IL-33 mRNA expression was found for COPD epithelial/moDCs co-cultures (compared to control, p = 0.02) epithelial/ moMφs co-cultures (p = 0.03) and triple co-cultures (p = 0.01) (compared to asthma)." (PMID 34168212, 2021). "The production and release of epithelial cytokines, including IL-33, IL-25, and TSLP, lead to the recruitment and activation of ILC2, which secretes mediators, such as IL-5 and IL-13, that augment allergic inflammation in the pathogenesis of virus-induced asthma exacerbation." (PMID 35008429, 2021). "IL-33 solicits particular interest in this context, as it has been shown to be released by necrotic AECs during IAV infection in humans and mice, it regulates lung immune responses to both viral and bacterial infections, and it is also increased in the lungs of asthma patients." (PMID 34960788, 2021). "In addition to IL-33, the epithelial cell-derived cytokines IL-25 and TSLP also have important roles in ILC2 activation and function in response to helminth infections, as well as type 2 inflammatory responses such as allergy and asthma." (PMID 34194431, 2021). "When compared to healthy subjects, the amounts of IL-33 and ST2 resulted in being significantly elevated in serum and bronchial biopsies taken from asthmatic patients, and the expression levels of this alarmin and its receptor are directly correlated with asthma severity." (PMID 34572294, 2021). "Despite the substantial role of IL-33 in driving Th2-mediated responses, ST2 deficient mice are not resistant to allergic asthma, suggesting that inhibition of IL-33 alone may not be sufficient for preventing asthma development." (PMID 34084159, 2021). "Interestingly, IL-33 stimulation increases collagen production only in lung fibroblasts from children with severe therapy-resistant asthma but not in lung fibroblasts from healthy adults." (PMID 32903501, 2020). "Obesity did not influence TSLP and IL-33 mRNA expression in any of the evaluated groups, but BMI might impact the IL-17A mRNA expression in asthma." (PMID 32842623, 2020). "More recently, ES-62 was found to inhibit IL-33/ST2/MyD88 signaling and modulate the pro-inflammatory responses resulting from crosstalk between ST2, FcεRI, and TLR4, which may contribute to reported protective effects of ES-62 in chronic models of asthma." (PMID 32983184, 2020). "Nevertheless, IL-33 through the intensification of TGF-β expression is involved in the stimulation of fibrosis and bronchial remodeling, including EMT, which might further contribute to the development and comorbidity of asthma and OSA." (PMID 31057533, 2019). "Indeed, in a murine asthma model, it was shown that IL1α release by pulmonary epithelial cells induces allergic sensitization to inhaled house dust mite via autocrine release of Th2-driving cytokines IL25, IL33, and TSLP." (PMID 31427886, 2019). "Taken into consideration the engagement in this process, in particular of mastocytes and their secretion of CXCL2, 4, 8, and other cytokines, there is no doubt regarding the etiopathogenic role of IL-33 in the development of asthma in response to various stimuli damaging bronchial epithelial cells." (PMID 31057533, 2019). "IL-33 induces an asthma-like phenotype in Rag2−/− mice, which lack mature lymphocytes, demonstrating that adaptive immune responses are not required to induce an asthma-like phenotype." (PMID 31191511, 2019).